IDH1 (isocitrate dehydrogenase (NADP(+)) 1)
Diseases named in the same sentence as IDH1 in open-access papers (continued):
Sharing a sentence is not in itself a finding about the gene and the disease.
glioma (continued). "While IDH1/2 mutations most commonly occur in Grade II and III gliomas, they are also present in approximately 5% of GBM that have progressed from lower grade gliomas, known as secondary GBM." (PMID 30647847, 2018). "DNA and mRNA were isolated from 21 fresh frozen human high-grade glioma samples (IDH1 mt n = 12, IDH1 wt n = 9)." (PMID 29428975, 2018). "Another target for peptide vaccines in glioma is IDH1, given that the IDH1 R132H mutation is expressed in the majority of secondary GBM and is thought to represent a driver mutation in glioma development." (PMID 29241354, 2018). "We demonstrated that glioma harboring mutant IDH1 epigenetically represses G0S2 expression, thereby suppressing surrounding cell invasion and resulting in a better prognosis." (PMID 30388142, 2018). "For example, we found evidence that IDH1 R132H is selected more strongly than IDH1 R132C in low-grade glioma and glioblastoma." (PMID 29748584, 2018). "Unusually, however, PC and PE levels are reduced in mutant isocitrate dehydrogenase 1 (IDHmut) gliomas that produce the oncometabolite 2-hydroxyglutarate (2-HG) relative to wild-type IDH1 (IDHwt) gliomas." (PMID 29619216, 2018). "Inhibitors of mutant isocitrate dehydrogenase 1 (IDH1) entered recently clinical trials for treatment of gliomas." (PMID 29662077, 2018). "The discovery of mutations in the isocitrate dehydrogenase genes 1 and 2 (IDH1, IDH2) in 2008 was a major breakthrough towards molecular biomarker-driven diagnosis of adult gliomas." (PMID 29098416, 2018). "One study focusing on IDH1 mutant gliomas found a continuous distribution of myeloid phenotypes ranging from more microglial on one extreme to more macrophage-like on the other." (PMID 30041684, 2018). "IDH1/2 mutation-driven downregulation of LDHA prevents glycolytic switch (Warburg effect) and limits the growth of gliomas." (PMID 29439493, 2018). "Nearly all IDH1-mutant gliomas contain methylated O-6-methylguanine-DNA methyltransferase (MGMT) genes, which sensitize tumors to temozolomide (TMZ) therapy." (PMID 29643764, 2018). "The isocitrate dehydrogenase 1/2 (IDH1/2) gene mutation is identified in >70% of WHO grades II and III gliomas and secondary glioblastomas and constitutes a discriminant between primary and secondary GBM." (PMID 29904027, 2018). "Here, the authors apply a MRS imaging method for 2HG detection and assessement of the pharmacodynamic effects of the mutant IDH1 inhibitor (IDH305) in 8 mutant IDH1 glioma patients." (PMID 29662077, 2018). "Mutations of both isocitrate dehydrogenase isoforms (IDH1 and IDH2) are linked to tumorigenesis and are detected in acute myeloid leukaemia, colorectal cancers, and in a large proportion of high grade gliomas and glioblastomas." (PMID 29772792, 2018). "Our analyses identified TAGLN2 as one of the significantly up-regulated genes in IDH1/2 WT compared to IDH1/2 mutant low(er) grade gliomas." (PMID 30647847, 2018). "The IDH1 and IDH2 mutations were subsequently indentified in the majority of lower grade gliomas, mostly in diffuse astrocytomas (62%), anaplastic astrocytomas (46%), oligodendrogliomas (77%), and anaplastic oligodendrogliomas (73%)." (PMID 29662659, 2018). "To further confirm the presence of synaptophysin-positive glioma cells in vivo, we used a tissue-microarray including three IDH1 positive gliomas." (PMID 30297697, 2018). "The metabolic and bioenergetic features were identified in glioma cells using wild-type and genetically engineered IDH1-mutant glioblastoma cell lines by metabolic analyses with Seahorse, protein expression studies and liquid chromatography-mass spectrometry." (PMID 30404651, 2018). "The most common mutations are IDH1 R132 and IDH2 R172, comprising roughly 90% of IDH mutations; the former is noted in more than 70% of grade 2/3 gliomas and in GBMs that progressed from these lower-grade tumors." (PMID 29899215, 2018).
glioma (continued). "The results revealed that low miR-770 levels were significantly associated with WHO pathological grade, IDH1 status and KPS score in glioma patients." (PMID 30524203, 2018). "In IDH1 (the cytosolic NADP-dependent isoform), almost all gliomas are associated with an active site R132H mutation, whereas in IDH2 (the mitochondrial NAD-dependent homolog), the main active site mutation is R172K." (PMID 29772792, 2018). "The survival analysis showed that younger age; IDH-1 mutations; higher albumin, AGR, and PNI levels; and lower NLR, PLR, and fibrinogen levels were favorable prognostic factors of OS in all gliomas and glioblastomas (GBMs)." (PMID 30154718, 2018). "Gliomas demonstrate epigenetic dysregulation exemplified by the Glioma CpG Island Methylator Phenotype (G-CIMP) seen in IDH1 mutant tumors." (PMID 29428975, 2018). "The mutation of IDH1 in glioma is associated with a hyper-methylation phenotype, which activates HIF and inactivates α-ketoglutarate in glioma." (PMID 30131700, 2018). "Similar to our patient-derived glioma tissues, cell lines expressing mutant IDH1 had decreased TAGLN2 protein levels compared to U87 MG IDH1/2 WT glioma cells." (PMID 30647847, 2018). "Recent studies carried out in appropriate animal models strongly support a role for mutant IDH1 in glioma formation." (PMID 30279357, 2018). "G0S2 levels were significantly higher for wild-type IDH1 than for mutant IDH1 among WHO grade III/IV gliomas." (PMID 30388142, 2018). "Through comprehensive investigation of the regulation of central carbon metabolism, we are able to show that glioma cells expressing mutant IDH1 increase the synthesis of proline through the activity of PYCR1, a mitochondrial NADH-oxidising enzyme." (PMID 29562167, 2018). "Previous studies have demonstrated that reorganization of the methylome and the resulting hypermethylator phenotype in gliomas is established by the presence of mutant IDH1/2." (PMID 30647847, 2018). "Specifically, despite effective reduction of D2-HG by small-molecule inhibitors specific to mutant IDH1, treated glioma cells, unexpectedly, accelerated proliferation and shortened survival in an animal model." (PMID 30416682, 2018). "Taken together, this study demonstrates a possible link between increased TAGLN2 expression, invasion and poor patient outcomes in IDH1/2 WT gliomas and identifies TAGLN2 as a potential novel therapeutic target for IDH1/2 WT gliomas." (PMID 30647847, 2018). "Then, the results from multivariate Cox regression analysis including HOXC8 expression, age at diagnosis, IDH1 status, gliomas grade and TCGA subtype showed that HOXC8 was an independent prognostic factor for glioma patients (p < 0.0001, HR = 1.247)." (PMID 32922885, 2018). "Given the success and enhanced potential of immune-checkpoint inhibitors in immunotherapy, we focused on the connections between genetic alterations affected by IDH1 mutations and immunological landscape changes and PDL-1 expression in gliomas." (PMID 29643764, 2018). "We demonstrate that when compared to IDH wildtype glioma cells and tumors, IDH1 mutant cells and tumors are enriched for gene sets associated with DNA repair, while wildtype cells have greater expression of gene sets associated with nucleotide biosynthesis." (PMID 29692895, 2018). "Many papers have generated their own system by stably transfecting an empty vector, wild-type IDH1 or R132H IDH1 into glioma cell lines." (PMID 30405699, 2018). "These suggest that GABA and glutamine can have an important role in energy production through substrate oxidation preferentially in IDH1 wild-type gliomas." (PMID 30404651, 2018). "Inhibitors of the mutant isocitrate dehydrogenase 1 (IDH1) entered recently in clinical trials for glioma treatment." (PMID 29662077, 2018).
glioma (continued). "While our study is limited by the availability of only one established heterozygous IDH1 mutant glioma cell line, the epigenetic regulation of transgelin, a homologue of TAGLN2, has been reported in multiple other cancer types." (PMID 30647847, 2018). "Inhibition of IDH2 (R140G) induced differentiation of AML cells, and inhibition of IDH1 (R132H) induced differentiation and impaired growth of glioma in in vitro and in vivo models." (PMID 29342092, 2018). "There is a growing evidence that molecular markers such as IDH1/2 mutations, MGMT promoter methylation, TERT promoter mutational status or 1p/19q co-deletion are important for diagnosis and prognosis of glioma patients." (PMID 29535343, 2018). "A more invasive phenotype is believed to contribute to worse prognoses in IDH1/2 WT LGGs compared to IDH1/2 mutant gliomas, among other proposed mechanisms." (PMID 30647847, 2018). "It is of interest to note that methylation of K27 is also inhibited by elevated levels of 2-hydroxyglutarate, originated from gain-of-function IDH1 mutations, associated with the CpG island methylator phenotype (G-CIMP) gliomas and glioblastomas." (PMID 30279357, 2018). "They further validated these findings and found increased expression of ZEB1 mRNA in IDH1-mutant grades II–III gliomas, and ZEB1 protein expression was more pronounced in these tumors." (PMID 32309604, 2018). "Mutations in IDH1 and IDH2 have been known to be a key development of many gliomas with information regarding outcomes and response to therapy." (PMID 30046944, 2018). "Isocitrate Dehydrogenase-1 (IDH1) is a driver gene in several cancers including brain tumors such as low-grade and high-grade gliomas." (PMID 29971034, 2018). "What is more, age at diagnosis, IDH1 status, gliomas grade, TCGA subtype was significantly related with survival time of glioma patients (p < 0.0001)." (PMID 32922885, 2018). "Our study sheds light on the metabolic effects in response to mutant IDH1 inhibition in glioma patients." (PMID 29662077, 2018). "Currently, AG-881 is in phase I clinical trial for AML patients with mutant IDH1/2, and a clinical trial for patients with glioma will begin soon (NCT02492737 and NCT02481154)." (PMID 28748451, 2018). "In particular, the results of this study show that IDH1 mutant gliomas are less vulnerable to radiation-induced DNA damage which draws into question the efficacy of radiation therapy for this subset of tumors." (PMID 29692895, 2018). "Here, we show initial evidence regarding the pharmacodynamic effects of mutant IDH1 inhibition in glioma patients." (PMID 29662077, 2018). "We also found higher mRNA expression of TAGLN2 in GBM compared to IDH1/2 WT gliomas of lower grades." (PMID 30647847, 2018). "The molecular mechanisms of the mutant IDH1 glioma are not fully understood, and the implications of mutant IDH1 inhibition are still a matter of debate." (PMID 29662077, 2018). "In summary, we have shown that TAGLN2 expression is silenced by promoter hypermethylation and therefore likely involved in the glioma hypermethylator phenotype of IDH1/2 mutant gliomas." (PMID 30647847, 2018). "Because of the relatively high portion of IDH1 mutated tumors, the separation of primary and secondary GBM (progressing from the low-grade gliomas) was performed on the basis of clinical information from the patient history, where possible." (PMID 29662659, 2018). "Heterozygous gain-of-function mutations in IDH1/2 (isocitrate dehydrogenase (NADP(+) 1/2; IDH) is traditionally a hallmark of a subset of gliomas associated with favorable patient outcomes." (PMID 29642018, 2018). "We further use human specimen of brain metastases and resected gliomas (IDH1 wildtype glioblastoma and IDH1 mutant oligodendroglioma) to further advance our technique to the clinical arena." (PMID 30686972, 2018). "This differential regulation of TAGLN2 provides further insight into the genetic, epigenetic and oncogenic differences between IDH1/2 WT and mutant gliomas." (PMID 30647847, 2018).
glioma (continued). "To this end, by employing an mRNA and proteomics profiling approach, we identified transgelin-2 (TAGLN2) to be differentially expressed between IDH1/2 WT and mutant gliomas." (PMID 30647847, 2018). "Mutated IDH1/2 can be functionally considered as highly specific tumor-associated neoantigens that could be targeted by immunotherapy; a vaccine targeting mutant IDH1 showed antitumor activity in a glioma animal model opening the possibility of new experimental therapies." (PMID 30386738, 2018). "Recently, several genes have been reported to be prognostic factors in gliomas, such as IDH1, FGFR3, Notch1." (PMID 30524204, 2018). "Previous studies demonstrated that IDH1 mutations frequently occurred in grade II and III gliomas and secondary GBM glioblastoma, but rarely in primary GBM; whereas IDH2 mutations occur in fewer than 3% of glial tumors." (PMID 30061525, 2018). "IDH1-mutant primary PCa tumors also manifested a similar phenotype, with levels of hypermethylation exceeding those of glioma or acute myeloid leukemia IDH1-mutant tumors." (PMID 30200539, 2018). "We are the first to identify TAGLN2 as a gene likely to be involved in the hypermethylator phenotype and further show that TAGLN2 undergoes epigenetic regulation in IDH1/2 mutant gliomas." (PMID 30647847, 2018). "Our global methylation analysis of low(er) grade gliomas from our institutional cohort showed that CpG sites corresponding to the TAGLN2 promoter are more highly methylated in IDH1/2 mutant compared to IDH1/2 WT gliomas." (PMID 30647847, 2018). "Here, we have shown that TAGLN2 functions as an oncogene in IDH1/2 WT gliomas and is expressed at significantly higher levels in IDH1/2 WT gliomas due to TAGLN2 promoter hypermethylation and subsequent gene silencing in IDH1/2 mutant gliomas." (PMID 30647847, 2018). "Altogether, this study demonstrates that IDH1 mutant gliomas are a distinct subclass of glioma with a less malignant, but also therapy-resistant, metabolic profile that will likely require distinct modes of therapy." (PMID 29692895, 2018). "This differential expression of TAGLN2 was primarily due to promoter hypermethylation in IDH1/2 mutant gliomas, suggesting involvement of TAGLN2 in the G-CIMP." (PMID 30647847, 2018). "Further, phase I, II and III clinical trials were planned and are ongoing to test the safety and efficacy of IDH1 inhibitors in different malignancies, such as glioma, cholangiocarcinoma, AML (NCT02074839, NCT02073994, NCT02719574, NCT02989857)." (PMID 29871612, 2018). "To characterize 5hmC in IDH1 mutant gliomas further, we examine 5hmC in a cohort of IDH1 mutant and wild-type high-grade gliomas (HGG) using a quantitative locus-specific approach." (PMID 29428975, 2018). "In this study, we show the initial evidence of the pharmacodynamics of a new mutant IDH1 inhibitor in glioma patients, using non-invasive 3D MR spectroscopic imaging of 2HG." (PMID 29662077, 2018). "We observed the mean D2-HG levels at 3,583 nmol per mg protein in IDH1R132H–PDGFB cells, a concentration similar to those in human IDH1R132H glioma cells and fourfold greater than that in IDH1–PDGFB cells." (PMID 30416682, 2018). "The wildtype IDH1 U87MG human glioma flank xenograft model was used to determine if MRK-A treatment effects were IDH1 mutant-specific." (PMID 29062039, 2017). "Somatic mutations in isocitrate dehydrogenase 1 (IDH1) and isocitrate dehydrogenase 2 (IDH2) have been detected in secondary glioblastomas, gliomas and acute myeloid leukemia (AML)." (PMID 28410203, 2017). "Despite being considered chemoresponsive IDH1 mutant gliomas commonly recur even after surgical resection and treatment with radiation and temozolomide, highlighting the need for new treatment options." (PMID 28178660, 2017). "Hotspot mutations in IDH1 and, less frequently, IDH2 occur in 80% of WHO grade II-III and secondary WHO grade IV gliomas and are ancestral events in the formation of these neoplasms." (PMID 28467784, 2017).
glioma (continued). "Alternatively, 13C MRS provides real-time, dynamic information on the metabolic fate of 13C α-KG, and thus directly probes the enzymatic activity of cytosolic mutant IDH1 in live glioma cells." (PMID 28629182, 2017). "Mutations in the cytoplasmic IDH1 and in the mitochondrial IDH2 mutations occur in various human cancers, including gliomas, glioblastoma, and acute myelogenous leukemias (AMLs)." (PMID 28352611, 2017). "In the case of gliomas, a codon change from CGT to “CAT” (c.395G>A and p.Arg132His) is the most frequent type of IDH1 mutation." (PMID 28403884, 2017). "In this report, we describe the effects of a brain-penetrant small molecule inhibitor of mutant IDH1 on in vitro and in vivo 2-HG production in mutant cell lines and patient-derived orthotopic glioma xenograft mouse models." (PMID 29062039, 2017). "Triple-positive (IDH1 and TERT mutation with 1p19q codeletion) glioma tended to be oligodendroglioma present with much better clinical outcome compared to TERT mutation only group who is glioblastoma inclined (median overall survival 39 months VS 18 months)." (PMID 28915860, 2017). "In IDH1-mutant glioma cells, AGI-5198 inhibited 2-HG production and cell growth in vitro and in vivo." (PMID 28092669, 2017). "This study provides a detailed and clinically relevant insight into the in vivo metabolism of IDH1‐mutant gliomas and points to novel metabolic vulnerabilities in these tumors." (PMID 29054837, 2017). "Recently, molecular biomarkers including the 1p/19q co-deletion, BRAF mutation, IDH1/2 mutation, and TERT mutation have been widely used in the diagnosis, treatment, and prognostic prediction of gliomas." (PMID 28978019, 2017). "Despite the diagnostic significance of glioma according to the new version the WHO criterion, the IDH1 mutation status was used to tailor personalized treatment regimens, including surgical extent and chemo-sensitivity." (PMID 28710497, 2017). "When transformed by expression of an exogenous mutant IDH1 gene, the NHA epigenetically resemble IDH1 mutant gliomas." (PMID 28178660, 2017). "In particular, IDH1 and 2 are present in over 80% of low-grade gliomas and a subset of glioblastomas." (PMID 28491867, 2017). "Mutations of isocitrate dehydrogenase 1 and 2 (IDH1 and IDH2) gene were recently discovered in vast majority of World Health Organization (WHO) grade II/III gliomas." (PMID 28052098, 2017). "Similar to findings in adult IDH1-mutant gliomas, we identify heterogeneous ATRX alterations among IDH1 mutant pHGG tumor pairs." (PMID 29084603, 2017). "At the same time, we explore the application of 5-FU in treatment of IDH1 R132H mutant glioma stable cells." (PMID 28052098, 2017). "Future experiments will need to be done to explore the treatment options targeting AKT-mTOR in IDH1 R132H mutant glioma both in vitro and in animal glioma tumor models." (PMID 28052098, 2017). "The mean SWI-LIV in IDH1-R132H negative gliomas (109.9; SD = 57.9) was significantly higher compared to IDH1-R132H positive gliomas (38.3; SD = 21.1; p < 0.0001)." (PMID 27300198, 2017). "Inhibitors of mutant IDH1 have been effective in lowering 2HG levels in vivo and reducing growth of glioma cells in vitro." (PMID 27752843, 2017). "GB10 is a novel and proprietary patient-derived IDH1 R132H mutant glioma model developed and characterized below." (PMID 29062039, 2017). "These mutations (mostly involving cytosolic IDH1, lesser so mitochondrial IDH2) have important consequences for the epigenome and cause extensive DNA methylation in IDH-mutant diffuse gliomas (‘glioma-CpG island methylator phenotype’/G-CIMP)." (PMID 28074274, 2017). "Of utmost importance for molecular classification and prognosis in gliomas is the status of the IDH1 gene." (PMID 28122345, 2017).